ANG (angiogenin)
Diseases named in the same sentence as ANG in open-access papers (continued):
Sharing a sentence is not in itself a finding about the gene and the disease.
metabolic disorders (13 papers, 2015 to 2025). "A recent study reported the transmission of angiogenin-mediated paternal inflammation-induced metabolic disorders including glucose intolerance and obesity to the offspring via sperm tsRNAs." (PMID 39825433, 2025). "Angiogenin-mediated tsRNAs regulate inflammation and metabolic disorders via targeting NLRP3 inflammasome." (PMID 39870617, 2025). "A recent study showed that angiogenin (ANG) in caput epididymis mediates paternal inflammation-induced metabolic disorders in offspring by sperm tsRNAs." (PMID 37993934, 2023). "The deletion of tRNA RNase (Angiogenin) in mice leads to a decrease in tsRNA production in sperm, which induces paternal inflammation and heritable metabolic disorders." (PMID 36552481, 2022). "Deletion of angiogenin prevents the inflammation-induced alteration of 5’-tsRNAs expression profile in sperm and abolishes the transmission of paternal inflammation-induced metabolic disorders to the offspring." (PMID 39825433, 2025). "Furthermore, it was recently reported that environmental changes can indirectly induce alteration of tsRNA expression levels in the sperm, and angiogenin (ANG) in the mouse caput epididymis regulates sperm tsRNAs and mediates paternal inflammation-induced metabolic disorders in the offspring." (PMID 39199264, 2024).
neurological disorders (7 papers, 2014 to 2025). "The present study examines the potential role of angiogenin (ANG), a known regulator of cell function and metabolism linked to neurological disorders, focusing in the neurogenic subventricular zone (SVZ)." (PMID 34234733, 2021). "So far, no human disease has been associated with mutations in Dnmt2, but similar to NSun2, also mutations in angiogenin are linked to neurological disorders." (PMID 25063673, 2014). "Loss-of-function mutations in angiogenin have also been associated with neurological diseases, supporting the hypothesis is that angiogenin rather exerts a neuro-protective role." (PMID 25063673, 2014).
adenocarcinoma (3 papers, 2015 to 2022). A common cancer characterized by the presence of malignant glandular cells. "Human angiogenin (hANG, or ANG) is a 123 residue 14.1 kDa protein first isolated from human adenocarcinoma cell-conditioned media." (PMID 34576228, 2021). "Angiogenin (Ang) was initially isolated from serum-free supernatants of an established human adenocarcinoma cell line (HT-29), but it was not a tumor-specific product." (PMID 25659096, 2015).
gastrointestinal tumors (1 paper, 2022). "Angiogenin, a well-known angiogenic factor, is crucial to the angiogenesis in gastrointestinal tumors." (PMID 36466652, 2022).
intestinal diseases (1 paper, 2023). "Overall, the significance of Ang4 as a crypt niche factor highlights its potential to facilitate the development of angiogenin-based treatment for intestinal diseases." (PMID 38020881, 2023).
urological disorders (1 paper, 2018). "Another multiplex panel analysis of proteins in urine samples of BC, healthy controls and other samples with varying urological disorders revealed that urine concentrations of IL-8, MMP-9 and 10, PAI-1, ANG, and APOE were significantly increased in subjects with BC compared to healthy controls." (PMID 30544619, 2018).
ANG also shares sentences with these, for which no sentence is quoted: Sepsis (15 papers); chronic kidney disease (9); Insulin resistance (9); pulmonary fibrosis (8); cognitive decline (7); renovascular hypertension (7); acute respiratory distress syndrome (6); Myocardial fibrosis (6); nasopharyngeal carcinoma (6); Nephropathy (6); breast tumors (5); Cognitive impairment (5); diabetic cardiomyopathy (5); Anxiety (4); cardiomyopathy (4); injury (4); malaria (4); Parkinson's (4); renal failure (4); renal fibrosis (4); steatosis (4); vascular disorder (4); atrial fibrillation (3); Crohn disease (3); dementia (3); Glucose intolerance (3); Hepatic steatosis (3); sarcoma (3); triple-negative breast carcinoma (3); Ureteral obstruction (3).
A further 149 diseases each share a sentence with ANG in 2 papers or fewer.